DKKL1 (dickkopf like acrosomal protein 1)
Description:
Involved in fertilization by facilitating sperm penetration of the zona pellucida. May promote spermatocyte apoptosis, thereby limiting sperm production. In adults, may reduce testosterone synthesis in Leydig cells. Is not essential either for development or fertility.
Synonyms: CT34; SGY-1; SGY1; SGY
Tractability: Antibody: UniProt places it where antibodies can reach, with medium confidence; UniProt predicts a signal peptide or a membrane-spanning region; its Gene Ontology location is reachable by antibodies, with medium confidence.
Gene: Protein-coding gene on chromosome 19 (49,361,783 to 49,375,116, forward strand). Ensembl gene ENSG00000104901.
Subcellular location: Secreted; Cytoplasmic vesicle, secretory vesicle, acrosome
Subcellular location (Human Protein Atlas): Acrosome; Equatorial segment; Vesicles; Mid piece; Predicted to be secreted
Gene Ontology:
Molecular function: co-receptor binding; receptor antagonist activity
Biological process: anatomical structure morphogenesis; negative regulation of canonical Wnt signaling pathway; negative regulation of testosterone biosynthetic process; penetration of zona pellucida; positive regulation of apoptotic process
Cellular component: acrosomal vesicle; extracellular region
Genetic constraint (gnomAD): Loss-of-function variants: 11 observed, 17.9 expected, observed/expected ratio (o/e) 0.61, 90% interval 0.39 to 1.02. The upper end of that interval is the gene's LOEUF score, 1.02, which puts it in group 4 of 6, group 1 being the genes least tolerant of losing a copy. Missense variants: 320 observed, 321.78 expected, observed/expected ratio (o/e) 0.99, 90% interval 0.91 to 1.09. Synonymous variants: 119 observed, 138.26 expected, observed/expected ratio (o/e) 0.86, 90% interval 0.74 to 1.
Homologues: Orthologues: chimpanzee DKKL1 (99% identical), macaque DKKL1 (94% identical), dog DKKL1 (76% identical), pig DKKL1 (73% identical), guinea pig DKKL1 (61% identical), mouse Dkkl1 (60% identical), rat Dkkl1 (53% identical).
Diseases named in the same sentence as DKKL1 in open-access papers:
DKKL1 is named in the same sentence as 24 diseases in open-access papers, as found by Europe PMC text mining. Sharing a sentence is not in itself a finding about the gene and the disease. The quoted sentences say what the papers report.
Anxiety (2 papers, 2019 to 2022). Intense feelings of nervousness, tension, or panic often arise in response to interpersonal stresses. "In our study, we show that this gene is upregulated in dioestrus compared to proestrus females, suggesting a possible role of cycling Dkkl1 expression in regulating anxiety levels across the oestrus cycle." (PMID 31253786, 2019).
colorectal cancer (2 papers, 2016 to 2025). A primary or metastatic malignant neoplasm that affects the colon or rectum. "DKKL1 (Dickkopf-like 1) is known to modulate the Wnt/β-catenin signaling pathway, a critical regulator of cellular proliferation and differentiation in colorectal cancer, and its expression has been linked to enhanced tumor invasiveness and metastasis." (PMID 40599850, 2025). "In colorectal cancer, CTAs such as DKKL1, FBXO39, and OIP5 hold great promise as therapeutic targets due to their overexpression and immunogenic properties." (PMID 40599850, 2025). "In view of this, the present study aims to identify lead CTL epitopes targeting DKKL1, FBXO39, and OIP5 CTAs for colorectal cancer." (PMID 40599850, 2025). "This study leveraged computational immuno-informatics tools to identify high-affinity HLA class I-restricted epitopes from DKKL1, FBXO39, and OIP5, providing a basis for the development of a peptide-based vaccine for colorectal cancer immunotherapy." (PMID 40599850, 2025). "This study identified CTL-specific epitopes from DKKL1, FBXO39, and OIP5 as potential targets for colorectal cancer immunotherapy." (PMID 40599850, 2025).
Azoospermia (1 paper, 2025). Absence of any measurable level of sperm,whereby spermatozoa cannot be observed even after centrifugation of the semen pellet. "In patients with azoospermia, the expression of DKKL1 in testicular tissue is significantly reduced or absent compared to that in normal testicular tissue." (PMID 40584277, 2025).
colon cancer (1 paper, 2025). "Moreover, the downregulation of DKKL1 has been linked to the progression of colon cancer." (PMID 40599850, 2025).
cryptorchidism (1 paper, 2012). The failure of one or both testes of a male fetus to descend from the abdomen into the scrotum during the late part of pregnancy. "Moreover, the screening of DKKL1 gene mutations in patients with SCOS, cryptorchidism and spermatogenic arrest by direct sequencing may help us to understand the role of DKKL1 in clinical male infertility." (PMID 22817830, 2012). "To further validate the function and role of DKKL1 in male infertility, we examined the DKKL1 mRNA transcript levels as well as protein levels among the patients with SCOS, cryptorchidism or spermatogenic arrest." (PMID 22817830, 2012). "RT-PCR results indicated that DKKL1 was not expressed in the testes of patients with either SCOS or cryptorchidism." (PMID 22817830, 2012). "No DKKL1 protein signal was detected in testis of patients with SCOS or cryptorchidism." (PMID 22817830, 2012). "An examination of the expression levels of DKKL1 in infertile male patients revealed that while no DKKL1 appeared in the testes of patients with Sertoli cell only syndrome (SCOS) or cryptorchidism, DKKL1 was observed with variable expression in patients with spermatogenic arrest." (PMID 22817830, 2012).
depression (1 paper, 2019). "Of note was that the overexpression of Dkkl1 in the ventral hippocampus, our area of interest, has been shown to induce increased depression-like behaviour in response to social defeat stress in male mice." (PMID 31253786, 2019).
infertile (1 paper, 2012). "To investigate the contribution of DKKL1 to spermatogenesis, we examined its expression in the testes of fertile and infertile men." (PMID 22817830, 2012).
male infertility (1 paper, 2012). The inability of the male to effect fertilization of an ovum after a specified period of unprotected intercourse. "A clearer understanding of the role of DKKL1/Dkkl1 in testes may help elucidate the biological principles underlying the increasing rate of male infertility and may provide targets for the development of a male contraceptive." (PMID 22817830, 2012).
polyp (1 paper, 2024). A usually exophytic mass attached to the underlying tissue by a broad base or a thin stalk. "DKK1 and DKKL1 showed a significant upregulation in polyp specimens, while WNT10B, GREM1, RSPO3, SFRP5, and GPC3 showed a downward trend." (PMID 38473810, 2024).
cancer (4 papers, 2016 to 2025). A tumor composed of atypical neoplastic, often pleomorphic cells that invade other tissues. "Compared to these efforts, our study uniquely focuses on the cancer-testis antigens DKKL1, FBXO39, and OIP5, which have been largely underexplored in CRC immunotherapy despite their selective overexpression and potent immunogenic potential." (PMID 40599850, 2025). "Previous research has shown that DKKL1 contributes to tumor cell invasion and metastasis, highlighting its importance in cancer progression." (PMID 40599850, 2025). "In our study DKKL1 was significantly overexpressed in cancer tissue and correlated positively with disease stage." (PMID 27635108, 2016).
tumor (3 papers, 2016 to 2025). "In contrast to neoantigen-based vaccines, which focus on targeting mutation-specific antigens unique to individual tumors, our multi-epitope vaccine targets conserved tumor-associated antigens (DKKL1, FBXO39, and OIP5) that are widely expressed across CRC patients." (PMID 40599850, 2025). "Among these CTAs: DKKL1, FBXO39, and OIP5 have emerged as particularly attractive targets for immunotherapy due to their specific overexpression in tumor tissues and roles in promoting oncogenesis." (PMID 40599850, 2025). "When the Wilcoxon signed-rank test was used, we noted that 6 of 18 (33%) CTAs tested, MAGEA3, OIP5, TTK, PLU1, DKKL1, and FBXO39, were significantly (p < 0.05) overexpressed in the tumor compared with normal tissue located ~5 cm away from the primary lesion." (PMID 27635108, 2016).
DKKL1 also shares sentences with these, for which no sentence is quoted: Alzheimer disease (1 paper); breast carcinoma (1); esophageal squamous cell carcinoma (1); head and neck squamous cell carcinoma (1); lung carcinoma (1); melanoma (1); multiple myeloma (1); multiple sclerosis (1); neurodegenerative disease (1); Parkinson disease (1); Sertoli Cell-Only Syndrome (1); Stroke (1); temporal lobe epilepsy (1).